AGAP6 (ArfGAP with GTPase domain, ankyrin repeat and PH domain 6)
Description:
Putative GTPase-activating protein.
Synonyms: AGAP-6; CTGLF3; bA324H6.1
Tractability: No criterion of Open Targets' tractability assessment is met for any kind of drug.
Gene: Protein-coding gene on chromosome 10 (49,982,190 to 50,011,654, forward strand). Ensembl gene ENSG00000204149.
Gene Ontology:
Molecular function: GTPase activator activity; GTPase activity
Genetic constraint (gnomAD): Loss-of-function variants: 28 observed, 50.74 expected, observed/expected ratio (o/e) 0.55, 90% interval 0.41 to 0.76. The synonymous counts are far from expectation, so gnomAD's model fits this gene poorly and the ratio says little. Missense variants: 488 observed, 750.55 expected, observed/expected ratio (o/e) 0.65, 90% interval 0.6 to 0.7. Synonymous variants: 198 observed, 273.78 expected, observed/expected ratio (o/e) 0.72, 90% interval 0.64 to 0.81.
Homologues: Paralogues in human: AGAP4 (98% identical), AGAP5 (96% identical), AGAP9 (90% identical), AGAP1 (62% identical), AGAP3 (48% identical), AGAP2 (43% identical), ACAP3 (19% identical), ACAP2 (18% identical), ASAP1 (17% identical), ASAP2 (17% identical), ACAP1 (17% identical), ARAP2 (16% identical), and 16 more.
Diseases named in the same sentence as AGAP6 in open-access papers:
AGAP6 is named in the same sentence as 3 diseases in open-access papers, as found by Europe PMC text mining. Sharing a sentence is not in itself a finding about the gene and the disease. The quoted sentences say what the papers report.
lymphoma (1 paper, 2025). A malignant (clonal) proliferation of B- lymphocytes or T- lymphocytes which involves the lymph nodes, bone marrow and/or extranodal sites. "Furthermore, by conducting summary‐data‐based Mendelian randomisation (SMR) analysis, we have identified novel genes that regulate immune cell function, including PSPHP1 and AGAP6, which have not been previously investigated in the context of lymphoma." (PMID 40360443, 2025).
Sepsis (1 paper, 2020). Sepsis is defined as life-threatening organ dysfunction caused by a dysregulated host response to infection. "Some selected genes were significantly higher expressed in sepsis as compared with MBC samples (CD24, CD177, MMP8, and TLR5), and in MBC compared with sepsis (HLA-DRA, CSF1R, and AGAP6/9)." (PMID 32958605, 2020).
cancer (1 paper, 2022). A tumor composed of atypical neoplastic, often pleomorphic cells that invade other tissues. "AGAP4 and AGAP6 have not been previously reported; they belong to the GTPase-activating protein family that play a vital role in cancer progression." (PMID 36100894, 2022).